EGFR (epidermal growth factor receptor)
Diseases named in the same sentence as EGFR in open-access papers (continued):
Sharing a sentence is not in itself a finding about the gene and the disease.
heart failure (51 papers, 2013 to 2025). Inability of the heart to pump blood at an adequate rate to meet tissue metabolic requirements. "Osimertinib has also been strong associated with QTc prolongation and cardiac failure relative to other EGFR-TKIs." (PMID 39267801, 2024). "EGFR receptor activation contributes to the growth and survival of cardiomyocytes, while impotent EGFR signaling is linked in transition from compensatory hypertrophy to heart failure." (PMID 34456633, 2021). "To date, no observational studies of baseline and on-treatment rates of cardiac failure, specifically in patients with EGFR mutation–positive NSCLC, have been published." (PMID 33530147, 2015). "Selective gene silencing of EGFR in the PVN led to a correction of multiple central and peripheral markers associated with heart failure implying that targeting brain EGFR might represent a novel approach in the treatment of MI-induced HF." (PMID 34408653, 2021). "Role in the assessment and monitoring of EGFR-TKIs-induced cardiotoxicity sST2 as a biomarker of inflammation, fibrosis, and myocardial stress in the diagnosis and prognosis of heart failure and myocardial infarction has been increasingly studied." (PMID 38983928, 2024). "The osimertinib group had a significantly higher likelihood of newly developed arrhythmia compared with the group receiving other EGFR TKIs, in addition to an increased likelihood of heart failure (eTable in Supplement 1)." (PMID 39636639, 2024). "Inhibition of the epidermal growth factor receptor (EGFR) signaling pathway by statins reduces blood pressure and pressure overload with slower onset of heart failure and amelioration of cardiac remodeling in vivo." (PMID 37887864, 2023). "We present the case of a 63-year-old man with EGFR-mutated NSCLC treated with osimertinib who developed new-onset non-ischemic cardiomyopathy with biventricular dysfunction and heart failure in the context of an enlarging pericardial effusion." (PMID 37908018, 2023). "Compared to other EGFR inhibitors (erlotinib, gefitinib, afatinib), and targeted therapies, osimertinib is strongly associated with QT interval prolongation, SVT, and heart failure." (PMID 36761953, 2023). "Cardiovascular adverse events (AEs), including QT prolongation, decreased left ventricular ejection fraction (LVEF), and heart failure, have emerged as potential AEs with certain EGFR TKI therapies." (PMID 34647107, 2021). "All these findings prompt us to investigate the possible role of the EGFR/ERK pathway in mediating the protective effects of ASI against heart failure in our future work." (PMID 33253607, 2020). "MiR-23a regulates cardiomyocyte apoptosis, a key pathogenesis factor of heart failure, by targeting manganese superoxide dismutase and the vasculogenesis of coronary artery disease via targeting epidermal growth factor receptor." (PMID 30717412, 2019). "Recent studies in flies and mammals show that both activation and inhibition of EGFR signaling pathways result in heart failure but involve different mechanisms." (PMID 27904993, 2017). "A research based on data from the U.S. Food and Drug Administration Adverse Event Reporting System (FAERS) demonstrated that the reporting OR (ROR) (95% CI) for heart failure and QTc prolongation in comparing osimertinib vs. other EGFR-TKIs was 2.2 (1.5–3.2) and 6.6 (3.4–12.8)." (PMID 39267801, 2024). "Osimertinib (EGFR TKI) can also induce cardiac failure, atrial fibrillation, and QT prolongation." (PMID 38450055, 2023). "Furthermore, rates of QT prolongation, cardiac failure, and atrial fibrillation were found to be higher when osimertinib compared with other EGFR-TKIs in FAERS12." (PMID 36380085, 2022). "In summary, we present an EGFR-positive NSCLC case with osimertinib-induced cardiac failure." (PMID 35677717, 2022).
heart failure (continued). "However, the results found that the reporting odds ratio for osimertinib compared with all other drugs was 5.4 for cardiac failure and 11.2 for QT prolongation, and compared with the 3 other EGFR TKIs, it was 2.2 for cardiac failure and 6.6 for QT prolongation." (PMID 35677717, 2022). "However, some EGFR inhibitor treatments may also lead to heart failure and atrial fibrillation." (PMID 39919333, 2025). "Osimertinib, an inhibitor of EGFR in the ErbB/HER family, also demonstrates some activity against the HER2 receptor, which may contribute to its cardiotoxic effects, which may manifest as heart failure, left ventricular dysfunction, conduction abnormalities, and myocardial injury or dysfunction." (PMID 40227578, 2025). "Interestingly a very recent study showed that increased EGFR signalling in the rat brain, namely within the hypothalamic paraventricular nucleus (PVN), may also play a key role in mediating myocardial-infarction-induced heart failure through enhancing ERK1/2-induced sympathetic overactivity." (PMID 34408653, 2021).
colorectal adenocarcinoma (49 papers, 2005 to 2025). The most common type of colorectal carcinoma. "For example, EGFR fusion mutation EGFR–SEPT14 was found in a patient with colorectal adenocarcinoma." (PMID 38201251, 2023). "EGFR was shown to be overexpressed in inflammatory bowel disease (IBD)-associated colorectal adenocarcinoma, and indeed, an increased level of EGFR was found in IBD mice-derived colorectal EVs which were also internalized by NIH3T3 fibroblast cells." (PMID 37296932, 2023). "It is well known that colorectal adenocarcinomas with RAS mutations often respond poorly to anti-EGFR antibody therapy." (PMID 29682203, 2018). "Although in colorectal adenocarcinoma the KRAS mutations are the most useful biomarker for selecting patients who are candidates for treatment with anti-EGFR monoclonal antibodies, its role in NSCLC as prognostic or predictive marker is less defined." (PMID 24782938, 2014). "We describe a case of colorectal adenocarcinoma, which was found to harbor a kinase domain mutation, G724S, in EGFR through whole genome sequencing." (PMID 24894453, 2014). "In total, 101 paraffin-section from colorectal adenocarcinoma samples were selected, and mutations in EGFR exon 18-21 were identified." (PMID 20184776, 2010). "Moreover, only 2 tumors demonstrated mutations, which, as is the case in colorectal adenocarcinoma, has been suggested to confer resistance to anti-EGFR antibody therapy in ASCC." (PMID 26498363, 2015). "The epidermal growth factor receptor (EGFR) expression is considered to play an essential role in the pathogenesis of colorectal adenocarcinoma." (PMID 38650801, 2024). "Human HT-29 colorectal adenocarcinoma cells, which are strongly positive for EGFR, were engrafted bilaterally in the mouse flank and used as models to evaluate drug delivery." (PMID 37376034, 2023). "The most critical signaling pathways associated with the epidermal growth factor receptor (EGFR) are RAS/RAF/MAPK and PIK3CA/PTEN-/AKT pathways, wherein colorectal adenocarcinoma the oncogenes and tumor suppressor genes of these pathways are mutated." (PMID 35463728, 2022). "In another study, high accumulation of boron compounds was observed in the HT-29 cell line derived from Homo sapiens colorectal adenocarcinomas, which also overexpress EGFR." (PMID 36499115, 2022). "A recent study reported that EGFR blockade reverts resistance to KRAS G12C inhibition in colorectal adenocarcinoma." (PMID 34647903, 2021). "KRAS (Kirsten rat sarcoma 2 viral oncogene homolog) is a major predictive marker for anti-epidermal growth factor receptor treatment, and determination of KRAS mutational status is crucial for successful management of colorectal adenocarcinoma." (PMID 32708359, 2020). "The epidermal growth factor receptor (EGFR) is over-expressed in 70–75% of colorectal adenocarcinomas (CRC)." (PMID 18700047, 2008). "Reporting EGFR immunostaining in conventional primary colorectal adenocarcinoma and its metastasis has extensively been studied recently." (PMID 17803816, 2007). "We assessed EGFR status of paired primary and distant recurrences of colorectal adenocarcinomas in a group of patients who received postoperative chemotherapy and compared their results with another group who did not receive any adjuvant therapy." (PMID 17163999, 2006). "There is immunohistochemical evidence to suggest that expression of epidermal growth factor receptor (EGFR) in primary colorectal adenocarcinoma predicts its expression in recurrent disease." (PMID 17163999, 2006). "There is established immunohistochemical evidence to suggest that EGFR expression in primary colorectal adenocarcinoma predicts its expression in recurrent disease." (PMID 17163999, 2006). "Our study shows that 57.6% of all recurrent colorectal adenocarcinomas will exhibit the same EGFR staining status of their primaries." (PMID 17163999, 2006). "Another group, found 72 cases of EGFR-positive expression in 82 resected colorectal adenocarcinomas (88%)." (PMID 15967033, 2005).
colorectal adenocarcinoma (continued). "Additionally, CP has promoted the growth of human colorectal adenocarcinoma H508 cells through increased EGFR/ERK1/2 signaling." (PMID 37624215, 2023). "To detect whether cytohesins are involved in the proliferation of HT-29 cells, we used the specific cytohesin antagonist SecinH3 and the EGFR-expressing human colorectal adenocarcinoma-derived HT-29 cells." (PMID 23420529, 2013). "PCA has also been demonstrated to suppress EGFR gene expression, which is an essential effector of the RAS/RAF/MEK/ERK pathway, in HCT-15 colorectal adenocarcinoma cells." (PMID 39932626, 2025). "Of note, EGFR clustering was reduced by LDL-DHA and BSA-DHA treatment in SW48 colorectal adenocarcinoma cells, which express high levels of EGFR containing a G719S mutation, which is constitutively active and resistant to kinase inhibitors." (PMID 33515553, 2021). "It is well known that EGFR and KRAS gene mutations act as positive and negative predictors, respectively, of therapeutic response to EGFR targeted therapies in colorectal adenocarcinoma." (PMID 24782938, 2014). "Interestingly, unlike in colorectal adenocarcinomas, significant responses are seen without the need for combination with EGFR inhibition." (PMID 37894318, 2023). "Multiple authors reported no Epidermal growth factor receptor, BRAF, KRAS, or Adenomatous polyposis coli (APC) mutations in GCA, suggesting that its molecular pathogenesis is significantly different from that of colorectal adenocarcinoma, although again this was not a unanimous finding." (PMID 35903705, 2022).
lymphoma (48 papers, 2010 to 2026). A malignant (clonal) proliferation of B- lymphocytes or T- lymphocytes which involves the lymph nodes, bone marrow and/or extranodal sites. "Our studies on lymphoma and EGFR mutation-positive NSCLC cell lines and primary samples have further confirmed the upregulation of PS on viable tumor cells." (PMID 37194236, 2023). "The effects of artesunate-induce inhibition on the expression of Hsp90aa1, Hsp90ab1, and associated client proteins (AKT, p-AKT, ERK, p-ERK, and EGFR) were investigated in the malignant lymphoma cell lines Daudi and CA-46 using western blotting." (PMID 37719860, 2023). "We tested the combined cytotoxic and phagocytic function of CER-1236 T cells in pre-clinical models of lymphoma and EGFR mutation-positive non-small cell lung (NSCLC) adenocarcinoma." (PMID 37194236, 2023). "Recent evidence has revealed that EGFR signaling is implicated in the progression of lymphoma." (PMID 35504024, 2022). "In this study, we demonstrated that the binding of artesunate to Hsp90 reduces the expression of its client proteins AKT, ERK, p-AKT, p-ERK, and EGFR, thereby blocking the G0/G1 phase → S phase of lymphoma cells and inducing apoptosis." (PMID 37719860, 2023). "Specifically, by inhibiting HSP90, artesunate reduces the expression of its client proteins (AKT, ERK, and EGFR), thereby suppressing lymphoma cell proliferation." (PMID 37719860, 2023). "A series of signaling pathways had been report involved in the proliferation, apoptosis, and survival of lymphoma cells, including EGFR signaling." (PMID 35504024, 2022). "Our comboFM method predicted combination partners to extensively explored ALK and EGFR inhibitors for lymphoma, which we were able to also validate in the experimental setting." (PMID 33262326, 2020). "The comboFM model identified also another unique drug combination effective against the SR cell line, the combination of EGFR inhibitor gefitinib with an approved chemotherapy lomustine for lymphoma treatment." (PMID 33262326, 2020). "Taken together, the data suggest that PLD2 acts in concert with EGFR to enhance mitogenesis and invasion in lymphoma cells." (PMID 27713341, 2010). "“Epigenetics”, “microenvironment”, “neurotoxicity”, “palliative care”, “anti-mitotic”, “angiogenesis and invasion”, “EGFR”, “lymphoma”, “TT” and “translational” had been repeatedly ranked in the top 20 fields in 2016–2018 with this method, in both predicted and actual fields." (PMID 30717468, 2019). "Simultaneously, elevated expression levels of EGFR, KIAA1199, NF-κB p50, and MSI1 were also confirmed in myelocytomas, fibromas, and lymphomas using WB." (PMID 36291177, 2022). "These include rituximab for CD20-expressing lymphomas, trastuzumab for HER2-amplified cancers, and cetuximab for EGFR-driven solid tumors." (PMID 36970051, 2022). "This study has established that PLD2 up-regulates EGFR expression, as well as EGF-induced Akt activation, in a murine lymphoma cell line." (PMID 27713341, 2010). "IHC analysis revealed that PDX tissues were typical EGFR‐internalization adenocarcinomas without lymphoma transformation." (PMID 39560161, 2025). "KEGG pathway analysis revealed that proteins upregulated in NR patients were enriched in cytokine-cytokine receptor interactions and TNF signal pathways in NSCLC, adherent junction and apoptosis in ASPS, and EGFR TKI resistance and complement coagulation cascades in lymphoma patients." (PMID 38349411, 2024).
gallbladder cancer (47 papers, 2009 to 2026). "The present case report demonstrates a complete response in liver metastasis and 90% partial response to primary disease in the presence of a tumor-associated EGFR mutation in patient with metastatic gallbladder cancer." (PMID 32622356, 2020). "Consistent with this, treatment with ERBB2‐specific, EGFR‐specific shRNA or with a covalent EGFR family inhibitor Afatinib inhibits tumor‐associated characteristics of the gallbladder cancer cells." (PMID 30304546, 2019). "In 1995, Lee & Pirdas13 were thefirst to describe an association between the membrane receptor EGFR and cases of gallbladder carcinoma and other bile duct tumors, and its correlation with gallbladderdysplasia and chronic calculous cholecystitis." (PMID 25004291, 2014). "There have been no previous reports of chemotherapy plus an EGFR-tyrosine kinase inhibitor (TKI) to treat gallbladder cancer or correlations of response with the mutation status of the tyrosine kinase domain of the EGFR gene." (PMID 20961434, 2010). "We previously reported that 15% of biliary tree and gallbladder carcinomas had EGFR gene mutations in the tyrosine kinase (TK) domain and that the mutations led to activation of one or both of the EGFR signal transduction pathways." (PMID 21087480, 2010). "In this report, we describe a case of advanced EGFR‐amplified gallbladder cancer that responded to combination therapy with the anti‐EGFR antibody necitumumab, GEM, and CDDP." (PMID 39540676, 2024). "Existing studies have reported that in gallbladder cancer tissues and cells, upstream or downstream molecules of PI3K/AKT signaling pathway, such as EGFR, HER2, and PTEN, etc., experience gene mutations, amplifications or expression dysregulation." (PMID 38398143, 2024). "In gallbladder cancer, EGFR is expressed in about 90% of cases, making it an attractive target for use in fluorescent imaging." (PMID 35701793, 2022). "Western blotting, flow cytometry, and confocal microscopy were performed to confirm that EGFR was expressed in gallbladder cancer cells." (PMID 35701793, 2022). "Our study is the first identify that SCEL can promote gallbladder cancer cell proliferation by EGFR/PI3K/AKT pathway, and SCEL can influence neutrophil extracellular traps formation through EGFR/IL8 axis." (PMID 33414368, 2021). "COX-2, c-Met, β-catenin, c-erbB2 and EGFR were over-expressed in 80%, 74%, 71%, 62%, and 11% of invasive gallbladder cancers, respectively." (PMID 33167334, 2020). "miR-145-5p was also shown to inhibit the progression of gallbladder cancer by targeting the epidermal growth factor receptor (EGFR)." (PMID 33375055, 2020). "Src and Ras oncogenes inhibit apoptosis of gallbladder carcinoma (GBC) cells by activating the epidermal growth factor receptor (EGFR) signaling pathway." (PMID 25895131, 2015). "All the indications are that there is a close relationshipbetween overexpression of EGFR and carcinogenesis in gallbladder carcinoma cases." (PMID 25004291, 2014). "This case report demonstrates a patient with stage IV gallbladder cancer who experienced a rarely encountered complete, prolonged response after treatment with an oral EGFR-TKI plus chemotherapy." (PMID 20961434, 2010). "In this study, we sought to demonstrate that the da Vinci Firefly camera and EGFR-targeted antibody conjugated with fluorescent material could be used for the detection of gallbladder cancer in tumor mouse models." (PMID 35701793, 2022). "In this study, we sought to demonstrate whether the da Vinci® surgical system and FireflyTM camera could detect EGFR-targeted fluorescent images in orthotopic mouse models of gallbladder cancer." (PMID 35701793, 2022). "In the context of miRNA-based therapy, miR-135a-loaded cationic immunoliposomes coated with anti-EGFR (Epidermal Growth Factor Receptor) antibodies (Anti-EGFR-CIL-miR-135a) were shown to inhibit gallbladder carcinoma invasion (GBC) and metastasis, and to promote apoptosis." (PMID 34072348, 2021).